MIR1197 (microRNA 1197)
Synonyms: hsa-mir-1197; MIRN1197; mir-1197
Gene: MicroRNA gene on chromosome 14 (101,025,564 to 101,025,651, forward strand). Ensembl gene ENSG00000221745.
Gene Ontology:
Biological process: miRNA-mediated post-transcriptional gene silencing
Cellular component: RISC complex
Homologues: Orthologues: chimpanzee ptr-mir-1197 (100% identical).